OR4K3 (olfactory receptor family 4 subfamily K member 3 (gene/pseudogene))
Description:
Odorant receptor.
Synonyms: OR4K3P; OR14-10
Gene: Protein-coding gene on chromosome 14 (19,868,197 to 19,869,143, reverse strand). Ensembl gene ENSG00000176290.
Subcellular location: Cell membrane
Pathways (Reactome):
Sensory Perception: Expression and translocation of olfactory receptors
Homologues: Orthologues: rabbit OR4K3 (66% identical). Paralogues in human: OR4K14 (49% identical), OR4K2 (48% identical), OR4K15 (48% identical), OR4K5 (47% identical), OR4K13 (46% identical), OR4L1 (46% identical), OR4K1 (46% identical), OR4F4 (45% identical), OR4F5 (45% identical), OR4K17 (45% identical), OR4F17 (44% identical), OR4F6 (44% identical), and 116 more.